UCA1 (urothelial cancer associated 1)
Diseases named in the same sentence as UCA1 in open-access papers (continued):
Sharing a sentence is not in itself a finding about the gene and the disease.
melanoma (31 papers, 2013 to 2025). A malignant, usually aggressive tumor composed of atypical, neoplastic melanocytes. "A study comparing the expression of six cancer-implicated lncRNAs in melanoma to their respective expression in paired adjacent healthy tissue, found elevated expression of UCA1 in melanoma, especially at advanced stages." (PMID 28350340, 2017). "In this mechanism, HOXB3 functions as a miR-28-5p target gene, while UCA1, which is overexpressed in melanoma, can bind miR-28-5p." (PMID 40563399, 2025). "A similar interaction was observed in melanoma, where lncLUADT1 and UCA1 affected tumor progression." (PMID 40563399, 2025). "Previously available literature described its increased expression in melanoma cells, as well as their reduced ability to migrate after Uca1 silencing." (PMID 38601651, 2024). "UCA1 also interacted with an anti-miR-185-5p gene to increase melanoma cells proliferation, migration, and invasion via control of the Wnt-β-catenin signaling pathway." (PMID 37245177, 2023). "FOXM1, also known as miR-507, is a tumor suppressor that interacts with the lncRNA UCA1, promoting accelerated melanoma development by targeting the G2/M phase." (PMID 37245177, 2023). "We have uncovered a potential role for the regulatory network motif UCA1/AKT1/hsa-miR-125b-1 in melanoma." (PMID 32703153, 2020). "In melanomas, Interaction between UCA1 and miR-507 inhibit FOXM1 protein degradation to enhance cell proliferation, invasion, and G0/G1 cell cycle arrest." (PMID 33204264, 2020). "A study on primary melanoma, metastatic melanoma and nevi from patients and melanoma cell lines showed that the UCA1 level is increased in primary and metastatic melanoma, as well as in cell lines, compared with nevi." (PMID 30499222, 2019). "UCA1 is upregulated in human melanoma tissues and cell lines and is involved in tumor cell proliferation, migration and invasion." (PMID 30499222, 2019). "UCA1-mediated regulation of FOXM1 was discovered, in melanoma cells, to be based on the ceRNA function of UCA1 for miR-507, resulting in an increased malignant ability of these cells." (PMID 29147648, 2017). "As a result, FOXM1, a target of miR-507, is downregulated upon UCA1 depletion in melanoma cell lines, resulting in the inhibition of cell proliferation." (PMID 28415644, 2017). "Expression of UCA1 is also higher in advanced stage (III/IV) compared to early stage (I/II) melanoma." (PMID 27686732, 2016). "UCA1 upregulation was correlated with poor differentiation, advanced lymph node classification, and metastasis of melanoma cells, while invasive and migratory capacities were remarkably diminished by UCA1 knockdown." (PMID 27686732, 2016). "Still, until now, no experimental validation has functionally linked TUG1 and UCA1 expression to melanocyte transformation and primary melanoma formation." (PMID 35159386, 2022). "Likewise, UCA1 overexpression correlates with tumor stage in melanoma patients and promotes proliferation and invasion by regulating the miR-28-5p/HOXB3 and miR-507/FOXM1 axes." (PMID 35159386, 2022). "The expression of urothelial cancer associated 1 (UCA1) has been positively correlated with melanoma stage and, although not statistically significant, with metastatic status." (PMID 34638331, 2021). "UCA1 promotes the progression of melanoma by sponging miR-28-5p." (PMID 31996265, 2020). "Knockdown of UCA1 inhibited melanoma cell migration suggest that it might be involved in tumor dissemination." (PMID 28350340, 2017). "MALAT1 and UCA1 are upregulated in melanoma and both may indicate lymph node metastasis in melanoma." (PMID 28415644, 2017). "Hence, in this study, we selected 6 well-documented lncRNAs associated with metastasis including MALAT1, HOTAIR, NEAT-1, HULC, MEG-3, and UCA1 to evaluate their expression in primary melanoma and matched lymph node metastasis tissues." (PMID 23862139, 2013).
melanoma (continued). "Additionally, the expression of lncRNA-UCA1 was upregulated in melanoma tissues compared to normal tissues, while the downregulation of UCA1 was controlled by direct binding with miR-507, resulting in cell proliferation, invasion, migration, metastasis and cell cycle arrest inhibition." (PMID 36601121, 2022). "Furthermore, UCA1 and hsa-miR-125b-1 participation were found in 90% of cancer pathways which might suggests that they play a role not only in melanoma progression but also in other metastatic tumors." (PMID 32703153, 2020). "Other studies identified the role of HOTAIR, MALAT1, BANCR, ANRIL, SPRY‐IT1, SAMMSON, UCA1, and SLNCR1 in melanoma patients and cell lines." (PMID 39764216, 2024). "The levels of UCA1 and MALAT-1 were remarkably more elevated in patients with melanoma compared to healthy controls, and their levels were associated with the stage of the disease." (PMID 36614156, 2022). "Several lncRNAs were studied because of the high expression levels in melanoma patients, including SPRY4-IT1, MALAT-1, BANCR, UCA1, HOTAIR, and SNHG8." (PMID 36614156, 2022). "For example, several lncRNAs have been dysregulated in melanoma, including HOTAIR, BANCR, UCA1, and MALAT-1, and related to invasion and metastasis." (PMID 35626352, 2022). "Several lncRNAs are also upregulated in melanoma including SPRY4-IT1, BANCR, HOTAIR, UCA1 and MALAT-1." (PMID 29343260, 2018). "Several studies have identified known lncRNAs that are abnormally expressed in melanoma, such as SAMMSON, HOTAIR, SLNCR1, BANCR, SPRY4-IT1, ANRIL, Llme23, UCA1, MALATA1, GAS5, H19, CASC15, PTENP1, and MIR31HG." (PMID 28225791, 2017). "UCA1 via miR-507-FOXM1 axis could be involved in cell proliferation, invasion, and G0/G1 cell cycle arrest in melanoma." (PMID 33330110, 2020). "Altogether, our analysis suggested that the expression profiles of nodes in motif 3 (UCA1/AKT1/hsa-miR-125b-1) can be used for quick assignment of metastatic or non-metastatic phenotypes to melanoma patients." (PMID 32703153, 2020). "Moreover, a subsequent mechanistic study demonstrated that UCA1 can interact with miR-507 and promote the inhibition of FOXM1 expression, leading to increased invasiveness and clonogenic potential of melanoma cells." (PMID 33203119, 2020). "Other lncRNAs involved in melanoma cell proliferation are LLME23, UCA1 and MALAT1." (PMID 30499222, 2019). "Levels of UCA1 and MALAT-1 were significantly upregulated in melanomas compared to normal controls, and were significantly higher at later stage (stage III and IV) compared to early stage melanomas (stage I and II)." (PMID 29343260, 2018). "HOTAIR expression was found to be significantly higher in lymph node metastases compared to primary melanoma, whereas several other lncRNAs, including MALAT1, Urothelial carcinoma-associated 1 (UCA1), and nuclear-enriched transcript 1 (NEAT1), showed no change in their expression patterns." (PMID 28350340, 2017). "The results of this study showed that network motif UCA1/AKT1/hsa-miR-125b-1 has the highest prediction accuracy (ACC = 0.88) for discriminating metastatic and non-metastatic melanoma phenotypes." (PMID 32703153, 2020).
cervical carcinoma (27 papers, 2017 to 2025). A carcinoma arising from either the exocervical squamous epithelium or the endocervical glandular epithelium. "LncRNA urothelial cancer associated 1 (UCA1) was reported to be connected with HK2 in cervical cancer." (PMID 36685972, 2022). "In cervical cancer cells, UCA1 was upexpressed and negatively associated with miR-206, and knockdown of UCA1 directly decreased VEGF through miR-206 upregulation, and thereby suppressed tumor growth, viability, migration, and invasion." (PMID 32190702, 2020). "UCA1 has also been implicated in cervical cancer, where its overexpression promotes resistance of cervical cancer cells to cisplatin." (PMID 28637507, 2017). "Moreover, it has been proven that UCA1 is associated with cisplatin resistance, and it can be used as a potential target for a novel therapeutic strategy for cervical cancer." (PMID 28970820, 2017). "Our results reveal that the lncRNA UCA1 is upregulated in cisplatin (DDP)-resistant cervical cancer tissues and HeLa cells." (PMID 40259885, 2025). "UCA1, is also upregulated in cervical cancer and promotes the upregulation of the glycolytic pathway and can regulate radio-resistance." (PMID 39912983, 2025). "In the CaSki cervical cancer cell line, the expression of miR-122-5p is diminished, whereas UCA1 and SOX2 are significantly upregulated." (PMID 40710326, 2025). "The interplay between miR-122-5p and UCA1 affects the self-renewal and tumor advancement of cervical cancer stem cells through the modulation of SOX2 expression." (PMID 40710326, 2025). "Knockdown of UCA1 using siRNA-based targeting was found to reverse radioresistance of cervical cancer cell lines (SiHa and HeLa)." (PMID 39912983, 2025). "This study elucidates the regulatory mechanism of the miR-122-5p/UCA1/SOX2 axis in the self-renewal of cervical cancer stem cells, offering a significant theoretical foundation for the advancement of novel therapeutic targets." (PMID 40710326, 2025). "Further analysis revealed that miR-204 was a target of UCA1, UCA1 sponged miR-204 thus increased KIF20A in cervical cancer." (PMID 36798768, 2023). "In cervical cancer tissues and cell lines, UCA1 was highly expressed, knocked down UCA1 inhibited proliferation and invasion." (PMID 36798768, 2023). "For example, UCA1 up-regulates and inhibits the growth of cervical cancer cells in cervical cancer, which is a potential target for the treatment of cervical cancer cells." (PMID 36530425, 2022). "Together, lncRNA UCA1 promoted cisplatin resistance in cervical cancer, suggesting that blockade of lncRNA UCA1 is a useful approach for cervical cancer therapy." (PMID 36438563, 2022). "The expression of UCA1 in cervical cancer tissues is higher than that in normal tissues, and similarly, UCA1 expression in cervical cancer cell lines (HeLa, SiHa, C33A, and CaSKi) is also higher than that in normal cells." (PMID 35692795, 2022). "For example, exosomal lncRNA urothelial cancer-associated 1 (UCA1) enhances CD133+ cervical cancer cell differentiation and self-renewal via micro-rRNA-122-5P/SOX2 axis and UCA1 silencing leads to inhibited cell proliferation and invasion." (PMID 35740618, 2022). "Recently, some studies have shown that UCA1 is abnormally expressed in many cancers, for example, colorectal carcinoma, cervical carcinoma, and GC." (PMID 34238213, 2021). "Previous studies have revealed that UCA1 regulates cervical cancer cell proliferation, migration, and invasion via targeting miR-145." (PMID 34238213, 2021). "Yao and colleagues showed that lncRNA UCA1 has increased expression levels in radioresistant cervical cancer cell lines and promotes glycolysis." (PMID 33652661, 2021). "The discovery of the UCA1/HK2/glycolysis pathway in the radiotherapy of cervical cancer provides a new method to improve the radiotherapy effect." (PMID 31850189, 2019). "LncRNA UCA1 has been shown to promote the proliferation and invasion of cervical cancer cells through regulating miR‐206 expression." (PMID 30410864, 2018).
cervical carcinoma (continued). "And they revealed overexpression of LncRNA UCA1 lead to radioresistance in cervical cancer." (PMID 36685972, 2022). "Thus, UCA1 upregulated KIF20A expression to exacerbate cervical cancer via sponging miR-204." (PMID 36798768, 2023). "In addition, KIF20A regulated by lncRNA UCA1, may promote cell proliferation during the growth of cervical cancer cells." (PMID 35410446, 2022). "Moreover, a previous study suggested that lncRNA UCA1 (ENST00000397381.4) could play an important role in the pathogenesis of cervical cancer." (PMID 28970820, 2017). "lncRNAs that have been investigated as potential biomarkers for cervical cancer include HOTAIR MALAT1, HIF1A-AS2, PRNCR1 and UCA1." (PMID 39912983, 2025). "In cervical cancer, a mounting number of lncRNAs, such as LINC00511 and UCA1, have been characterized, and their regulatory mechanisms have been well defined." (PMID 39201624, 2024).
lymph node metastasis (27 papers, 2016 to 2024). "Regarding the clinicopathological data, the higher expression of UCA1 was associated with multifocality and marginally significantly with lymph node metastasis." (PMID 38277283, 2024). "For example, upregulation of lncRNA UCA1 expression level is significantly associated with lymph node metastasis and high TNM stage of GC patients, and UCA1 depletion inhibits GC cell migration and invasion abilities." (PMID 36760720, 2023). "Recent studies have demonstrated that UCA1 is closely associated with clinicopathological characteristics, including vascular invasion, lymph node metastasis and TNM stage, and can be used as a prognostic biomarker of diseases." (PMID 33777227, 2021). "UCA1 is closely associated with tumor size, histological differentiation, stage of lymph node metastasis, depth of invasion, vascular invasion, OS, RFS and prognostic biomarkers." (PMID 33777227, 2021). "And overexpression of UCA1 is associated with high lymph node metastasis rates, high distance metastasis rates and late TNM stage indicating UCA1 has an oncogenic role in GC." (PMID 32328192, 2020). "Studies have shown that the dysregulation of UCA1 is closely associated with the clinicopathological characteristics of cancer, such as lymph node metastasis (LNM) and overall survival (OS)." (PMID 30918102, 2019). "The expression level of UCA1 is significantly increased and is closely associated with lymph node metastasis, which is consistent with the TCGA database." (PMID 30464170, 2018). "Higher UCA1 expression was associated with lymph node metastasis, TNM stage, and poor overall survival (OS) in GC patients." (PMID 29516678, 2018). "Statistical analysis indicated that UCA1 expression was significantly associated with tumor size, lymph node metastasis, and TNM stage." (PMID 28624787, 2017). "Wang and coworkers found that UCA1 levels were associated with histological grade and lymph node metastasis in NSCLC." (PMID 27329842, 2016). "Notably, significantly elevated UCA1 expression in the tissues was correlated with multifocality, whereas lymph node metastasis and high UCA1 levels were slightly associated." (PMID 38534790, 2024). "However, the same study, in conjunction with another, revealed a crucial association between UCA1 and clinicopathological features, including poor prognosis, lymph node metastasis, advanced FIGO stage, and shorter PFS." (PMID 38534790, 2024). "validated the association between high expression of UCA1 and lymph node metastasis of OSCC." (PMID 33520725, 2020). "The expression level of UCA1 in tumor tissues was positively associated with lymph node metastasis (P = 0.004), distance metastasis (P = 0.015) and higher TNM stage (P = 0.035), but not with other clinicopathological parameters including age, gender and T stage." (PMID 32328192, 2020). "MALAT1, NKILA and UCA1 are associated with lymph node metastasis." (PMID 29416703, 2018). "Furthermore, we demonstrated that higher UCA1 expression is associated with lymph node metastasis, TNM stage, and worse OS in GC patients." (PMID 29516678, 2018). "Furthermore, the relationship between UCA1 and clinicopathologic factors verified that UCA1 expression was positively associated with lymph node metastasis and TNM stage in patients (P < 0.05)." (PMID 29516678, 2018). "And overexpression of UCA1 is associated with high lymph node metastasis rates and late TNM stage indicating UCA1 has an oncogenic role in GC and may act as a prognostic factor of advanced GC." (PMID 28569779, 2017). "From the pooled results, it found that increased UCA1 was significantly associated with lymph node metastasis (OR = 2.98, 95% CI: 2.06–4.30, P = 0.000), distant metastasis (OR = 3.14, 95% CI: 1.77–5.58, P = 0.000), and poor clinical stage (OR = 2.76, 95% CI: 2.08–3.68, P = 0.000)." (PMID 27517147, 2016).
lymph node metastasis (continued). "They observed that OC tissues exhibited more elevated UCA1 expression than the benign and normal ovarian specimens, while this overexpression was significantly associated with some clinicopathological characteristics, including staging, grade, peritoneal effusion, and lymph node metastasis." (PMID 38534790, 2024). "All analyzed OC tissues manifested UCA1 upregulation, a finding that was notably associated with FIGO staging, histological grade, peritoneal effusion, prognosis, and lymph node metastasis in the majority of cases." (PMID 38534790, 2024). "The in vivo experiment validated the previous findings, while the overexpression of UCA1 in the VSCC tissues was associated with advanced clinical stage disease and lymph node metastasis." (PMID 38534790, 2024). "For example, a bioinformatics analysis study showed that FAM95B1 and UCA1 were correlated with cervical lymph node metastasis, tumor staging, and TC prognosis." (PMID 32377223, 2020). "Additional study suggests that overexpression of UCA1 is significantly related to CRC patients with lymph node metastasis." (PMID 31480503, 2019). "Several literatures established a statistically significant relationship between high UCA1 expression and lymph node metastasis or prognosis." (PMID 30918102, 2019). "The pooled odds ratio (OR) and hazard ratio (HR) with 95% confidence interval (CI) using random/fixed-effect were used to identify the relationship between UCA1 and lymph node metastasis (LNM) or overall survival (OS) of cancer patients." (PMID 30918102, 2019). "High UCA1 expression levels were significantly correlated with advanced T category (P = 0.034), late clinical stage (P = 0.021), and worse lymph node metastasis (P = 0.02)." (PMID 28327194, 2017). "Expression of HIF1A-AS2 and UCA1 was higher in patients with lymph node metastasis at the time of diagnosis (P < 0.05), and expression of ANRIL was higher in patients with BC with high Ki67 score than low one (P < 0.05)." (PMID 28248879, 2017). "The correlation between the UCA1 level and the clinical features of PCa patients revealed that advanced pathological stage (I/II, n = 25) and NSCLC lymph-node metastasis were significantly associated with UCA1 expression." (PMID 28209917, 2017). "This meta-analysis collected all eligible studies and explored the relationships between UCA1 expression and lymph node metastasis (LNM) or overall survival (OS)." (PMID 27713161, 2017). "For instance, the patients with high UCA1 level in cancerous tissues were suggested to suffer from elevated lymph node metastasis (LNM) and distant metastasis (DM) rate in numerous cancers; nevertheless, this association has not been detected in other studies." (PMID 28074092, 2016). "The positive correlation of UCA1 and MMP14 was additionally demonstrated in the epithelial OC tissues (EOC), where UCA1 levels were increased and associated with the International Federation of Gynecology and Obstetrics (FIGO) stage, lymph node metastasis, and poor prognosis." (PMID 38534790, 2024). "Finally, VSCC tissues exhibited decreased miR-103a and overexpressed UCA1 levels, with the latter being significantly correlated with advanced clinical stage and lymph node metastasis." (PMID 38534790, 2024). "Furthermore, overexpression of UCA1 is closely associated with clinicopathological characteristics, including poor prognostic factors, such as TNM stage, vascular invasion and lymph node metastasis." (PMID 33777227, 2021). "GC patients with lymph node metastasis showed significantly higher UCA1 expression levels." (PMID 30464170, 2018). "According to these findings, we carried out this meta-analysis to explore the relationships between UCA1 expression and lymph node metastasis or overall survival, and to evaluate whether UCA1 could serve as a common molecular marker for LNM and OS." (PMID 27713161, 2017).